ITGA6 (integrin subunit alpha 6)
Diseases named in the same sentence as ITGA6 in open-access papers (continued):
Sharing a sentence is not in itself a finding about the gene and the disease.
leukemia (continued). "The growth rate of the AML1/shITGA6 cells was reduced, and these cells could not be maintained in culture, whereas the AML1/shITGB4 grew at rate similar to the parental UCSD/AML1 control cells, suggesting that the signal transduction of ITGA6 is essential for the maintenance of leukemia cells." (PMID 22295105, 2012). "The expression of ITGA6 is principally responsible for the increased cell adhesion capability and survival of EVI1-high leukemia cells." (PMID 37444576, 2023). "Also, the integrin alpha 6 gene (ITGA6, encoding CD49f), shown in several studies to be upregulated in HSC, playing an important role in HSC homing to the BM niche, and associating with poor therapy response in ALL, was among the top 5 upregulated genes in the CD34‐positive leukemias." (PMID 35271751, 2022). "Taken together, the results demonstrated that ITGB4, ITGA6, ITGA9, and VE-cadherin are the candidate integrin genes with increased adhesion ability in EVI1high leukemia cells." (PMID 22295105, 2012). "Two EVI1low (K562 and U937) and three EVI1high (UCSD/AML1, PT9 and PT11) leukemia cell lines were co-cultured with MC3T3-E1 cells, and the mixed cultures were subsequently treated with anti-ITGA6 or anti-ITGB4 antibody or the control isotype anti-rabbit IgG." (PMID 22295105, 2012). "Because the increased adhesion ability of the AML cells increased their resistance to chemotherapy, and the expression of ITGA6 was significantly higher in AML cases in relapse, ITGA6 might be a novel molecular target in EVI1high leukemia cells." (PMID 22295105, 2012). "Therefore, the expression of ITGA6 and ITGB4 was EVI1 dependent, and the increased expression of ITGA6 and ITGB4 in EVI1high leukemia cells increased their ability to adhere to the osteoblastic MC3T3-E1 cell line." (PMID 22295105, 2012). "Two leukemia (UCSD/AML1 and MOLM1) and two primary human AML (PT9 and PT11) cells lines were cultured on matrigel and treated with or without anti-ITGA6, ITGB2, ITGB3, or ITGB4 antibodies." (PMID 22295105, 2012). "The ability of the three EVI1high leukemia cells to bind to MC3T3-E1 cells was significantly reduced upon treatment with anti-ITGA6 or anti-ITGB4 antibody, whereas the binding ability of the two EVI1low leukemia cells did not change." (PMID 22295105, 2012). "Two days after treatment, the binding activity of all four cell lines was significantly reduced by the treatment with anti-ITGA6 or anti-ITGB4 antibodies; however, isotype IgG, anti-ITGB2 or anti-ITGB3 antibodies did not inhibit the binding of EVI1high leukemia cells to matrigel." (PMID 22295105, 2012).
gastric cancer (6 papers, 2013 to 2026). A primary or metastatic malignant neoplasm involving the stomach. "The interaction between the extracellular matrix (ECM) and ITGA6 subsequently activates the FAK/AKT pathway in gastric cancer cells, exacerbating the peritoneal metastasis of gastric cancer." (PMID 41188920, 2025).
lung fibrosis (6 papers, 2016 to 2024). "Itga6/FAK/PI3K/AKT signaling cascade pathway has been reported to be an important signaling pathway in silica-induced pulmonary fibrosis." (PMID 37215989, 2023). "The results of function–rescue assays also clarified that the functional role of miR-542-5p in the regulation of pulmonary fibrosis was dependent or partially dependent on the participation of Itga6." (PMID 30467286, 2018). "A recent report reveals that human IPF lung myofibroblasts express high levels of ITGA6 in vitro and in vivo and genetic ablation of ITGA6 in collagen-expressing mesenchymal cells protects mice against bleomycin injury-induced experimental lung fibrosis." (PMID 35980387, 2022). "In conclusion, miR-542-5p has a potential function for reducing the proliferation of fibroblasts and inhibiting silica-induced pulmonary fibrosis, which might be partially realized by directly binding to Itga6." (PMID 30467286, 2018).
colon carcinoma (5 papers, 2013 to 2023). "Similarly, ITGA6 alone has been used to isolate highly tumorigenic colon cancer stem cells." (PMID 37444576, 2023).
renal carcinoma (5 papers, 2016 to 2025). A carcinoma arising from the epithelium of the renal parenchyma or the renal pelvis. "have shown that Twist2 is involved in the progression of renal cancer by regulating ITGA6 and CD44 in the ECM-receptor interaction pathway." (PMID 39944833, 2025). "The results of immunohistochemical analysis indicate that the expression levels of COL9A3, GPC4, and ITGA6 in renal cancer tissue are higher than those in normal tissue, whereas the expression levels of FREM2, ITGA9, and P3HI are lower than in normal tissue." (PMID 38365923, 2024). "Twist2 may promote the migration and invasion of renal cancer cells by regulating the expression of ITGA6 and CD44." (PMID 38254353, 2024). "Twist-mediated transformation of renal cancer cells led to reduced expression of ITGA6." (PMID 27705936, 2016).
acute lymphoblastic leukemia (4 papers, 2023 to 2025). Leukemia with an acute onset, characterized by the presence of lymphoblasts in the bone marrow and the peripheral blood. "According to Scharff and collaborators, BCP-acute lymphoblastic leukemia distribution to the CSF is adversely linked with ITGA6." (PMID 37444576, 2023). "In acute myeloid leukemia and acute lymphoblastic leukemia cells, ITGA6 overexpression has also been linked to a poor prognosis." (PMID 37444576, 2023). "In addition, the expression of CD49c is also favorably linked with the ITGA6 expression in pre-B-acute lymphoblastic leukemia." (PMID 37444576, 2023). "Studies found that downregulation of ITGA6 or specific ITGA6-neutralizing antibody treatment inhibits acute lymphoblastic leukemia invasion to the central nervous system." (PMID 40198125, 2025). "ITGA6 is strongly expressed in most acute lymphoblastic leukemia patients, and its interaction with laminin enhances the development of CNS disease and the maintenance of minimal residual disease (MRD) after chemotherapy." (PMID 37444576, 2023). "Aside from motility, PI3K inhibition reduces cell surface expression of ITGA6 in acute lymphoblastic leukemia cells and limits CNS metastasis." (PMID 37444576, 2023). "In contrast, in spite of common CNS involvement, ITGA6 expression is low in B-acute lymphoblastic leukemia with KMT2A rearrangement." (PMID 37444576, 2023). "The ablation of ITGA6 from Ph+ acute lymphocytic leukemia cells results in cell cycle suppression and an increase in the proportion of cells in the G0/G1 and G2/M phases." (PMID 37444576, 2023). "ITGA6 expression in acute lymphoblastic leukemia cells from archival bone marrow biopsies of individuals with acute lymphoblastic leukemia is related to the incidence of CNS relapse, irrespective of other criteria thought to enhance the probability of CNS disease involvement." (PMID 37444576, 2023). "Interestingly, survivin, an antiapoptotic IAP family member, is increased by chemotherapy while reduced by treatment with P5G10, an antibody against ITGA6, in acute lymphoblastic leukemia cells." (PMID 37444576, 2023). "Nonetheless, Src inhibitors diminish the production of ITGA6 in B-acute lymphocytic leukemia cells." (PMID 37444576, 2023). "Moreover, ITGA6 expression is substantially more common in CD34+ pre-B-acute lymphoblastic leukemia than in CD34- pre-B-acute lymphoblastic leukemia." (PMID 37444576, 2023). "Treatment with the antibody against ITGA6 and P5G10 de-adhered acute lymphoblastic leukemia cells from the stroma and reduced stromal support in the face of chemotherapeutic damage." (PMID 37444576, 2023). "Furthermore, rather than ITGA6 expression, subsequent investigations found that ITGA5 and ITGA9 expressions are positively linked with CSF colonization in primary B-acute lymphoblastic leukemia samples." (PMID 37444576, 2023).
epidermolysis bullosa (4 papers, 2012 to 2024). Epidermolysis bullosa (EB) is a group of genetic skin diseases that cause the skin to blister very easily. "Thus, this case adds to the reported phenotype of ITGA6 disease since it is the first to show absence of an epidermolysis bullosa phenotype in the setting of pyloric atresia and nail dysplasia." (PMID 39583125, 2024).
head and neck squamous cell carcinoma (4 papers, 2016 to 2023). A squamous cell carcinoma that arises from any of the following anatomic sites: lip and oral cavity, nasal cavity, paranasal sinuses, pharynx, larynx, and salivary glands. "In head and neck squamous cell carcinoma (HNSCC), these miRNAs were found to inhibit migration and invasion through targeting of the focal adhesion laminin–integrin pathway (LAMC2, ITGA6 and LOXL2)." (PMID 31906022, 2019). "Besides, miR-150-5p and − 3p targets ITGA3 (integrin alpha 3), ITGA6 (integrin alpha 6), and TNC (tenascin C) in head and neck squamous cell carcinoma." (PMID 37924077, 2023).
hypertrophic cardiomyopathy (4 papers, 2020 to 2025). A condition in which the myocardium is hypertrophied without an obvious cause. "Aberrant regulation of these genes, including PKP2, ITGA6, and seven are important for cytoskeleton and cell-cell and cell-matrix interactions and are associated with cardiomyopathy, arrhythmogenic R ventricular cardiomyopathy and hypertrophic cardiomyopathy." (PMID 32477331, 2020).
liver cancer (4 papers, 2019 to 2023). An epithelial or non-epithelial malignant neoplasm that arises from the liver. "Given that CAP2 was already identified as a marker for early-stage liver cancer patients with negative alpha fetoprotein (AFP), we decided to focus our research analysis on the potential of ITGA6 as a diagnostic marker for early-stage liver cancer." (PMID 37627184, 2023). "One potential area for further research involves investigating the molecular pathways of ITGA6 in the onset of liver cancer." (PMID 37627184, 2023). "Among those genes, CLDN1, ITGA6 and ID2 have been reported to promote EMT, cell migration and proliferation in liver cancer cells, and the resminostat/sorafenib drug combination reduced the mRNA level of these genes (significantly for CLDN1 p = 0.0008, ITGA6 p = 0.0009)." (PMID 33953226, 2021).
lung adenocarcinoma (4 papers, 2020 to 2025). A carcinoma that arises from the lung and is characterized by the presence of malignant glandular epithelial cells. "Among the ATGs in female lung adenocarcinoma, there was a significant relationship between ITGA6 and its survival prognosis." (PMID 36959587, 2023). "Moreover, high ITGA6 expression was involved in the occurrence and development of lung adenocarcinoma, and ITGA6 overexpression abolished the effects of miR-302a-5p to induced NSCLC cell proliferation and migration." (PMID 33317527, 2020).
Obesity (4 papers, 2015 to 2025). Accumulation of substantial excess body fat. "Unfortunately, despite conducting in vivo genetic loss-of-function studies on the two leading candidate genes, Pdk1 and Itga6, we were unable to unambiguously point to a single causal gene that mediates the obesity phenotype." (PMID 36717164, 2023). "We hypothesized that genetic variation in or near Pdk1 or Itga6 causing reduced Pdk1 and Itga6 expression would promote obesity and impaired glucose tolerance." (PMID 36717164, 2023). "Using congenic mice, we found that obesity was affected by a ∼316 kb region, with only two known genes, pyruvate dehydrogenase kinase 1 (Pdk1) and integrin α 6 (Itga6)." (PMID 36717164, 2023). "Thus, Itga6 is also both a functional and positional candidate gene to mediate the obesity effects at the Moo1 locus." (PMID 36717164, 2023). "We hypothesized that reduced ITGA6 activity would promote obesity and tested this hypothesis using mice with partial deletion of Itga6." (PMID 36717164, 2023). "Thus, there is a possibility that these sequence changes leading to a gain or loss of function or other ESTs in the Moo1V strain region may alter obesity, instead of reduced Pdk1 or reduced Itga6 expression." (PMID 36717164, 2023).
adenoma (3 papers, 2012 to 2022). A neoplasm arising from the epithelium. "An Itga6-knockout mouse has been reported and develops normal crypts; however, it is susceptible to colitis and adenoma formation at later stages." (PMID 36350252, 2022).
colorectal tumors (3 papers, 2015 to 2018). "In this work, we used ITGA6, a well-characterized integrin transcript up-regulated in a majority of colorectal tumors as proof of concept using distinct approaches." (PMID 26895101, 2016). "Multivariate mathematical models demonstrated an association between hyperexpression of the ITGAV and ITGA6 integrins and GS, and also between the ITGA3 integrin and DFS, in patients with colorectal tumours." (PMID 26674523, 2015). "The final multivariate prognostic model achieved was composed of the ITGAV and ITGA6 integrins, which were found to correlate with GS, thereby suggesting that hyperexpression of these genes represents an independent action in reducing the survival of colorectal tumour patients." (PMID 26674523, 2015). "In conclusion, a multivariate mathematical model was generated that demonstrated an association between hyperexpression of the integrins, ITGAV and ITGA6, and GS, and also between the ITGA3 integrin and DFS, in patients with colorectal tumours." (PMID 26674523, 2015).
COVID-19 (3 papers, 2021 to 2023). A disease caused by infection with severe acute respiratory syndrome coronavirus 2. "Classification rules based on our study demonstrated that a relatively high expression of ITGA6 in CD4+ T cells may indicate COVID-19." (PMID 35928229, 2022). "The comparative analysis of gene expression among patients with COVID-19 and other SARS-CoV-2 infection systems showed that non-structural protein-mediated integrins such as ITGA6 are expressed in the lungs." (PMID 35928229, 2022).
head and neck cancer (3 papers, 2023 to 2025). A primary or metastatic malignant neoplasm affecting the head and neck. "Recent evidence shows that high expression of ITGA5 and ITGA6 in head and neck cancers is associated with increased infiltration of immunosuppressive cells, reflecting an exhausted tumor immune microenvironment." (PMID 41347085, 2025). "ITGA6 has emerged as a significant predictive marker of radioresistance, with its silencing attenuating radioresistance in head and neck cancer cells." (PMID 38493128, 2024). "The database shows that the ITGA6 and PTHLH are highly relevant to head and neck cancer, which are specifically expressed in the tissue." (PMID 37555363, 2023).
heart failure (3 papers, 2018 to 2024). Inability of the heart to pump blood at an adequate rate to meet tissue metabolic requirements. "We found that the four core genes (Tsc22d3, Itga6, Ermn, Sult1a1) were associated with immune system diseases, drug-related side effects and adverse reactions, chemical and drug-induced liver injury, neurological disorders, heart failure, mental disorders, and neural tube defects." (PMID 38843390, 2024). "FLNA, ITGA6, ITGA1, and MDK may play an important role in neurons in heart failure with DCM." (PMID 38310240, 2024).
junctional epidermolysis bullosa (3 papers, 2019 to 2021). "Mutations in the ITGA6 or ITGB4 gene, encoding for the integrin α6β4 subunits result in the skin blistering disease junctional epidermolysis bullosa (JEB) associated with pyloric atresia (JEB-PA)." (PMID 32796709, 2020). "Mutations in LAMA3, LAMC2, COL17A1, ITGA6, and ITGB4 are associated with the blistering skin disorder junctional epidermolysis bullosa and cause severe enamel hypoplasia, grooves and enamel pitting." (PMID 31417410, 2019).
seminoma (3 papers, 2020 to 2023). A radiosensitive malignant germ cell tumor found in the testis (especially undescended), and extragonadal sites (anterior mediastinum and pineal gland). "Altogether, these results revealed the key role of TFAP2C in promoting migration and invasion by directly regulating genes such as FOSL1, LYPD3 and ITGA6 in the seminoma cell line, promoting further study to understand its role in seminoma tumorigenesis." (PMID 38123589, 2023). "This suggests that, in contrast to the hypomethylated profile and copy number variants commonly observed in GCNIS-derived lesions, including seminomas, primary testicular ITGA6+ cells remain genetically stable during prolonged cell culture." (PMID 32176716, 2020). "Seminomas displayed a severely global hypomethylated profile, including loss of genomic imprinting, which we did not detect in cultured primary testicular ITGA6+ cells." (PMID 32176716, 2020). "DNA methylation patterns of cultured human testicular cells, sorted for ITGA6, do not overlap with those found in seminomas, indicating cultured cells do not acquire a seminoma signature." (PMID 35444616, 2022). "Differential methylation analysis revealed altered regulation of gamete formation and meiotic processes in cultured primary testicular ITGA6+ cells but not in seminomas." (PMID 32176716, 2020). "Lastly, seminomas displayed a number of characteristic copy number variations that were not detectable in primary testicular ITGA6+ cells, either before or after culture." (PMID 32176716, 2020). "The pivotal POU5F1 marker was hypomethylated in seminomas but not in uncultured or cultured primary testicular ITGA6+ cells, which is reflected in the POU5F1 mRNA expression levels." (PMID 32176716, 2020). "Compared to seminoma, the uncultured and cultured ITGA6+ PTCs do not harbor large-scale CNVs nor show signs of oncogene or retrotransposon activation in terms of regional DNA demethylation." (PMID 32176716, 2020).
small cell lung carcinoma (3 papers, 2017 to 2021). Small cell lung cancer (SCLC) is a highly aggressive malignant neoplasm, accounting for 10-15% of lung cancer cases, characterized byrapid growth, and early metastasis. "In addition, there were 6 common KEGG pathways in the CIN-CC group (p < 0.01), namely, the adipocytokine signaling pathway, small cell lung cancer (ITGA6, PIAS3, and LAMC2), pathways in cancer, the Toll-like receptor signaling pathway, graft versus host disease, and the TGF-beta signaling pathway." (PMID 34174849, 2021).
acute myeloid leukaemia (2 papers, 2023 to 2024). "ITGA6 was first discovered as a cancer stem cell or leukemic stem cell marker in acute myeloid leukemia and has been linked to its resistance." (PMID 37444576, 2023). "ITGA6 is also substantially higher in cases of acute myeloid leukemia recurrence than in cases of acute myeloid leukemia remission." (PMID 37444576, 2023). "Noteworthy, the ROS-dependent expression level of HIF-1α is elevated in EVI1-high acute myeloid leukemia-transformed cells with ITGA6 overexpressed." (PMID 37444576, 2023). "It has been reported that relapsed B-acute lymphoblastic leukemia and EVI1+ acute myeloid leukemia patients have considerably higher levels of ITGA6 expression." (PMID 37444576, 2023).
atherosclerosis (2 papers, 2020 to 2025). A disease characterized by the build-up of fatty material and calcium deposition in the arterial wall resulting in partial or complete occlusion of the arterial lumen. "For example, combinations of pan-EC, LEC, and ITGA6 antibodies can be used to purify or enrich this population in developmental or disease models (e.g. atherosclerosis)." (PMID 32091396, 2020). "In atherosclerosis, ECs communicated extensively with pericyte cells and SMCs through LAMININ (LAMA5-(ITGA1+ITGB1), LAMA5-(ITGA7+ITGB1), LAMB2-(ITGA6+ITGB4), LAMB2-(ITGA6+ITGB1)) and COLLAGEN (COL4A1-(ITGA1+ITGB1), COL4A2-(ITGA1+ITGB1)) pathways." (PMID 40225569, 2025).
cervical squamous cell carcinoma (2 papers, 2015 to 2024). A squamous cell carcinoma arising from the cervical epithelium. "However, there are challenges in identifying specific markers for cervical squamous cell carcinoma (CCSC), including ABCG2, MSI1, PROM1 (CD133), ITGA6 (CD49f), KRT17 (CK17), SOX2, and Pou5f1 (OCT4)." (PMID 38651153, 2024).